PARK7 (Parkinsonism associated deglycase)
Diseases named in the same sentence as PARK7 in open-access papers (continued):
Sharing a sentence is not in itself a finding about the gene and the disease.
pancreatic neuroendocrine tumor (1 paper, 2020). Pancreatic endocrine tumor, also known as pancreatic neuroendocrine tumor (PNET), describes a group of endocrine tumors originating in the pancreas that are usually indolent and benign, but may have the potential to be malignant. "Another study reported that PARK7 is highly expressed in 52.5% of pancreatic neuroendocrine tumors, and its elevated expression is correlated with aggressiveness, disease progression, and reduced survival of patients with pancreatic neuroendocrine tumors." (PMID 32357493, 2020).
renal cell carcinoma (1 paper, 2020). "Cisplatin treatment reduces the expression of PARK7; however, PARK7 inhibits the cisplatin-induced apoptosis of renal cell carcinoma cells." (PMID 32357493, 2020).
seminoma (1 paper, 2021). A radiosensitive malignant germ cell tumor found in the testis (especially undescended), and extragonadal sites (anterior mediastinum and pineal gland). "Of them, 14-3-3γ, ezrin, filamin A, Parkinsonism-associated deglycase 7 (PARK7), vimentin and vinculin, were validated in CS I seminoma patient cohort." (PMID 34771736, 2021). "The clinicopathological features and data on the PARK7 protein expression level from the TCGA database were used to confirm the IHC data and to review the prognostic power of PARK7 in CS I seminomas." (PMID 34771736, 2021). "It seems that deregulated expression of filamin A, PARK7 and 14-3-3γ in RTI-positive CS I seminoma might be implicated in the pathogenesis and progression of this disease and may help to identify patients with poor prognosis." (PMID 34771736, 2021). "Indeed, CS I seminoma patients from the TCGA database with PARK7 expression levels lower than the mean displayed worse OS compared to patients with higher PARK7 expression." (PMID 34771736, 2021). "While 14-3-3γ, ezrin, filamin A, PARK7, vinculin and vimentin could be analysed in cohort of CS I seminoma patients using IHC to validate their clinical relevance, IHC evaluation in the case of caldesmon and 14-3-3β failed (data were non-homogenous and suboptimal)." (PMID 34771736, 2021). "Therefore, more data are required to address the potential role of PARK7 in RTI-positive phenotype and prognosis of CS I seminoma patients." (PMID 34771736, 2021). "Hence, it seems that worse prognosis of RTI-positive CS I seminoma patients, manifested as a weak response to CDDP-based chemotherapy, could be associated, at least in part, with low levels of mitochondrially localized PARK7, which may be a result of overall low levels of retained PARK7." (PMID 34771736, 2021). "Notably, RTI-positive CS I seminomas showed decreased expression of PARK7 and filamin A, when compared with -negative cases." (PMID 34771736, 2021). "We observed lower levels of PARK7 in TCs of RTI-positive vs. -negative CS I seminoma patients." (PMID 34771736, 2021).
squamous cell carcinoma (1 paper, 2015). A carcinoma arising from squamous epithelial cells. "Only PARK2 and PARK7 in the ADC group showed significantly higher mRNA expression than those in the SQC group, which revealed that PARK2 and PARK7 may play a more important role in normal lung cells that transform into adenocarcinomas than those that become squamous cell carcinomas." (PMID 26245297, 2015).
xerostomia (1 paper, 2025). Dryness of the mouth resulting from reduced salivary secretion. "The downregulation of key proteins involved in oxidative stress and neurodegenerative diseases, encoded by PARK7, GLO1, GLUD2, VDAC2, UQCRC1, and UNC5C, including the 20S proteasome core complex proteins, highlights a possible mechanistic link to xerostomia pathophysiology." (PMID 40806170, 2025).
cancer (148 papers, 2006 to 2025). A tumor composed of atypical neoplastic, often pleomorphic cells that invade other tissues. "DJ-1 (PARK7) plays a critical role in cellular defence mechanisms against oxidative stress and has been linked to poor prognosis across various cancer types." (PMID 41009755, 2025). "PARK7 protein (DJ-1) is linked to various cancer types mainly; it influences the cancer cells transforming activity being with H-Ras/Myc, which primarily affects the S phase of the cell cycle by translocating from the cytoplasm to the nucleus." (PMID 40231252, 2025). "Firstly, we explored the gene expression profiles of SNCA (encoding for α‐syn) and PARK7 (encoding for DJ‐1) in different cancer types using TCGA datasets." (PMID 38189631, 2024). "PARK7/DJ-1 protein has been associated with PD and certain forms of cancer." (PMID 32477265, 2020). "As described in this review, recent studies on the expression of PARK7 have provided fundamental insights into the mechanisms underlying the functions of PARK7 in cancer progression, including the suppression of apoptosis, redox sensing, and serving as a marker of chemoresistance." (PMID 32357493, 2020). "Additionally, secreted PARK7 has been identified as a high-risk factor for the pathogenesis and survival of various cancers." (PMID 32357493, 2020). "Additionally, dimethyl fumarate induces the apoptosis of cancer cells by inhibiting the induction of GABPA/PARK7 by mutated Kirsten rat sarcoma 2 viral oncogene homolog (KRAS)." (PMID 32357493, 2020). "DJ-1, also known as Parkinson’s disease protein 7 (PARK7), is an emerging oncogenic biomarker with high expression levels reported in various types of cancer, including breast, pancreatic, and supraglottic cancers." (PMID 41465166, 2025). "α-synuclein, PTEN, PINK1, DJ-1 (PARK7), LRRK2, and tau (MAPT) are critical for neuronal integrity, yet their mutations or aberrant expression are also observed in various cancers." (PMID 41516242, 2025). "Previous studies suggested that after activation of the Wnt/β‐catenin signalling pathway by PARK7, cancer progression was promoted." (PMID 37987202, 2024). "PARK7 involved in stemness of glioblastoma stem cells (GSCs), and origin and development of uveal melanoma, suggesting its importance in cancer." (PMID 37987202, 2024). "More and more evidence suggests that Wnt/β‐catenin contributes to cancer progression, and previous study also confirmed that PARK7 activated the Wnt pathway, thereby promoting cancer development." (PMID 37987202, 2024). "Since both SNCA and PARK7 appeared to be significantly up‐regulated in SKCM in the pan‐cancer analysis, we further validated these results using the TCGA datasets." (PMID 38189631, 2024). "The protein deglycase DJ-1, also known as Parkinson's disease protein 7 (PARK-7), was identified as an oncogene that is upregulated in several types of cancer." (PMID 37065371, 2023). "Previously, the expression of PARK7/DJ-1 was mainly investigated regarding malignant tumors and neurodegenerative diseases." (PMID 35743072, 2022). "DJ-1 (PARK7) is known as an oncogene and its abnormal expression is related to the poor prognosis of various types of malignant tumors." (PMID 36408174, 2022). "The multifunctionalhuman Parkinson’s diseaseprotein 7(PARK7/DJ1) is an attractive therapeutic target due to its link withearly-onset Parkinson’s disease, upregulation in various cancers,and contribution to chemoresistance." (PMID 36149939, 2022). "The approach of molecular pathologic epidemiology (MPE), which is the epidemiology-based molecular classification of cancer, is essential for a better understanding of the link between PARK7 and cancer progression." (PMID 32357493, 2020).
cancer (continued). "The inhibition of the phosphatase activity of PTEN, the activation of AKT, and the increase in the transforming activity of cancer cells are higher in the presence of the C106S mutant than in the presence of the wild-type PARK7 protein." (PMID 32357493, 2020). "PARK7 has been found in high concentrations in body fluids of cancer patients suggesting its potential as a non-invasive cancer biomarker." (PMID 32635403, 2020). "PARK7 has been identified as a potential therapeutic target for the treatment of neurodegenerative diseases and cancer." (PMID 32357493, 2020). "Consistent with its implication in various pathological processes, including PD, several lines of evidence indicate that the expression of PARK7 is involved in the clinicopathology of various types of cancer." (PMID 32357493, 2020). "PARK7 significantly increases the transforming activity of cancer cells together with H-Ras/Myc and has been found to be translocated from the cytoplasm to the nucleus in the S phase of the cell cycle." (PMID 32357493, 2020). "Clinical trials have demonstrated that the migration and in vitro tumor formation of cancer cells that overexpress PARK7 are significantly reduced following treatment with anti-ERBB3 antibodies." (PMID 32357493, 2020). "Apart from the implication of PARK7 in the pathogenesis of PD, recent studies on PARK7 emphasize its key importance as an oncogene in the pathogenesis of cancer." (PMID 32357493, 2020). "PARK7 enhances the proliferation and aggressiveness of cancer cells by regulating the activity of various proteins via a direct interaction." (PMID 32357493, 2020). "Recent studies have demonstrated that PARK7 is secreted into the bloodstream and is involved in the progression of cancer." (PMID 32357493, 2020). "There are some common pathogenetic factors shared by PD autosomal recessive Parkinsonism and some types of cancer, such as the proteins PARKIN, PINK1 (PTEN induced putative kinase-1), and DJ-1 (Parkinsonism associated deglycase)." (PMID 33066407, 2020). "All autoantibody assays showed a statistically significant difference between CaP and non-cancer samples except for PARK7." (PMID 31404106, 2019). "Zinc-α2-glycoprotein (AZGP1), Flotillin-2 and Protein/nucleic acid deglycase DJ-1 (PARK7) were proposed as biomarkers for cancer diagnosis." (PMID 30158500, 2018). "Genetic studies provide additional understanding, since many familial PD genes have been associated with cancer, such as parkin (PARK2), PINK1 (PARK6), DJ-1 (PARK7), and LRRK2 (PARK8)." (PMID 27375474, 2016). "Stress-insult is a common theme across human health, with the antioxidant PARK7 (DJ-1) playing a central role in protecting against oxidative stress in cancer, cardiovascular disease and neurodegeneration." (PMID 26825309, 2016). "Here, we examined the regulation of reactive oxygen species (ROS) and of the antioxidant protein DJ-1 (PARK-7), which increases with cancer progression and acts to lessen oxidative damage to malignant cells, in relationship with SM severity." (PMID 27611333, 2016). "Next, we investigated whether SNCA and PARK7 expression are related to the survival prognosis in patients from various cancer types including SKCM." (PMID 38189631, 2024). "In such scenario, some genetic/molecular resemblances shared by both cancer and neuronal cells would not be surprising, and genes such as PARK7 (which encodes the protein DJ-1) fit well into this scenario." (PMID 36923654, 2023). "Also known by the alternative name PARK-7, it has been identified as an oncogene that is upregulated in several types of cancer." (PMID 36874678, 2023). "Thus, a multifunctional protein like PARK7 represents a prime candidate explaining the pathological interactions between cancer (GBM) and PD, which occur in the anatomically different regions yet in same organ." (PMID 36923654, 2023).
cancer (continued). "Although it was originally identified as an oncogene product, the role of PARK7 in cancer is largely unknown and remains to be elucidated." (PMID 34771736, 2021). "The first marker, DJ1, also known as Parkinson’s disease-associated protein 7 (PARK7), is a multifunctional protein promoting cell proliferation and playing an important role in cancer pathogenesis and progression by modulating the tumor suppressor PTEN." (PMID 34203959, 2021). "Notably, PARK7 is secreted by TCs into the bloodstream in many cancers and can be detected in the sera of cancer patients; its serum levels therefore correlate with disease progression and were proposed to serve as a potential prognostic biomarker in cancer." (PMID 34771736, 2021). "PARK7 is a redox sensor that protects cancer cells from oxidative stress." (PMID 32357493, 2020). "PARK7 induces cancer progression by inhibiting the expression of PTEN." (PMID 32357493, 2020). "The increase in the stability of PARK7 by striatin 3 (STRN3) enhances the survival of cancer cells." (PMID 32357493, 2020). "The expression of PARK7 is necessary for the acquisition of chemoresistance in cancer cells." (PMID 32357493, 2020). "Apart from its role in neurodegenerative disorders, numerous studies have suggested that PARK7 acts as a mitogen-dependent oncogene that plays a crucial role in the progression of various types of cancer and has been identified as a novel oncoprotein involved in the Ras transduction pathway." (PMID 32357493, 2020). "Nevertheless, the functions of PARK7 in cancer progression remain mostly unknown, necessitating the characterization of PARK7 in the pathogenesis of cancer by further studies." (PMID 32357493, 2020). "The continuous studies using these PARK7 inhibitors may need more evaluations for the therapeutic application of cancers and neurodegenerative diseases." (PMID 32357493, 2020). "Secreted PARK7 may be involved in the pathogenesis of other types of cancer." (PMID 32357493, 2020). "The cleavage of PARK7 by MMPs may play a role in the pathogenesis of cancer." (PMID 32357493, 2020). "Identification of the novel regulatory functions underlying the acquisition of cancer stem cells and drug resistance by PARK7 through the application of the MPE in cancer progression will provide novel and practical information that could aid the development of novel therapeutic strategies." (PMID 32357493, 2020). "The expression level of the DJ-1(PARK7) in HCC were analyzed by using the TCGA-LIHC( including normal liver tissue 50 cases, paracancerous 50 cases, cancer tissue 374 cases), HPA database and immunohistochemical testing." (PMID 38168113, 2024). "Among other chaperones, PARK7 (Parkinson protein 7) and PPIA (Peptidylprolyl Isomerase A) are upregulated and secreted by cancer cells." (PMID 37835519, 2023). "The overexpressed PARK7 protein interacts with the anti-apoptotic protein BCL2L1, increasing its mitochondrial localization, with effects in tumorigenesis, cancer cells proliferation, metastasis, recurrence and resistance to chemotherapy." (PMID 36500393, 2022). "PARK7 protein is overexpressed in downregulated JTB condition in MCF7 BC cell line; like in other various types of cancer, it suppresses apoptosis in tumor cells." (PMID 36500393, 2022). "PARK7 binds to human epidermal growth factor receptor 3 (ERBB3), a therapeutic anti-cancer target, and increases the stability of ERBB3 by inhibiting its ubiquitination." (PMID 32357493, 2020). "Proteomic studies and pathway analysis revealed that PARK7 is highly expressed in DHA-resistant cell lines, and the upregulation of PARK7 protects cancer cells from DHA-induced ROS and apoptosis by increasing the stability of Nrf2." (PMID 32357493, 2020). "In this study, we identified DJ-1/PARK7 (Parkinson Protein 7) as a novel interaction partner of HER3 and demonstrated the potential of DJ-1 as a biomarker for anti-HER3 cancer therapy." (PMID 27582551, 2016).
cancer (continued). "ABS has effects on the targets on cancer therapy like SND1, KPNA2, and PARK7." (PMID 35958818, 2022). "PARK7 requires the presence of the reduced form of the C106S mutant for inhibiting PTEN activity, inducing proliferation, and increasing the transformation of cancer cells." (PMID 32357493, 2020). "STRN3 also increases the expression of PARK7 by inhibiting the proteasome-mediated degradation of PARK7 and subsequently activates AKT by enhancing the stability of PARK7 and increasing the formation of protein-protein complexes for protecting cancer cells from oxidative stress." (PMID 32357493, 2020). "Moreover, ABS affects the potential targets on cancer therapy such as SND1, KPNA2, and PARK7." (PMID 31240215, 2019).